CRP (C-reactive protein)
Diseases named in the same sentence as CRP in open-access papers (continued):
Sharing a sentence is not in itself a finding about the gene and the disease.
infection (continued). "The same attention to the control of active infection is needed when treating patients affected also by cardiovascular diseases (CVD): it has been demonstrated how high serum levels of c-reactive protein (CRP) are major predictors for high serum and salivary levels of endothelin 1 (ET-1)." (PMID 32295150, 2020). "Extremely high CRP concentrations > 100 mg/l occur in about 12% of patients in a third opinion veterinary hospital and are indicative of a severe systemic disease with guarded prognosis and are observed due to various etiologies such as trauma, infection, immunopathy, and malignant neoplasia." (PMID 32434519, 2020). "In addition, infection-related biomarkers such as CRP and ESR were also significantly decreased." (PMID 33147282, 2020). "In our study, infection severity, but not mortality, was associated with D-dimer and CRP elevation." (PMID 33126565, 2020). "C-reactive protein (CRP), which is a well-known indicator of various infectious or inflammatory conditions, enhances Toll-like receptor-mediated superoxide release from neutrophils, potentially increasing oxidative stress, but also protecting the host from infection." (PMID 32326479, 2020). "In addition, CRP is an indicator of the body’s inflammatory response after pathogen infection." (PMID 32669467, 2020). "CRP levels present may be raised dramatically within 72 h due to infection." (PMID 32103450, 2020). "Moreover, a previous study suggested that CRP could mediate the host’s response to Staphylococcus aureus, including the protective function against infections and the role in increasing phagocytosis of pathogens." (PMID 33235597, 2020). "However, detecting infection by measuring neonate CRP levels is often unsatisfactory." (PMID 33211747, 2020). "The cohort as a whole was then analysed to create a model for PJI using pre-operative factors: increased medical risk of infection, age, type of joint, pre-operative inflammatory markers (WBC count, CRP and ESR) and whether the operation was a revision surgery." (PMID 32566455, 2020). "We hypothesize that in order to protect mice against late-stage infection, a structural change in CRP is needed, followed by the interaction between structurally altered CRP and recruited factor H on the pneumococcal surface, and that was not happening in mice." (PMID 33117400, 2020). "Also the level of the initial clinical suspicion of infection, the infant’s clinical progress and current condition should be reconsidered each day, including assessment of “reassuring” levels and trends of CRP when deciding timepoint for withdrawing of antibiotic treatment." (PMID 33218324, 2020). "Based on this finding, elevated CRP levels may be of concern for infectious progression; nevertheless, infection is not the only condition that will cause CRP to rise." (PMID 31375075, 2019). "Among the serum markers, although serum CRP in infection-triggered patients was significantly higher than other clinical AE-IIPs types, the serum procalcitonin levels was significantly higher in infection-triggered AE-IIPs than in patients with all total AE-IIPs." (PMID 31852459, 2019). "CRP and leptin but not IL-6 were significantly higher in the Ob group regardless of any underlying health condition, the progress of pregnancy, or the presence of any complication or infection." (PMID 30909605, 2019). "In the presence of long-standing HCV infection, which is quite common since the infection remains asymptomatic for a long time, the continued replication of the virus in the liver cells may decrease their ability to produce IL-6, and consequently CRP." (PMID 30813467, 2019). "Hence, our modelling strategy for infections did not aim to utilise CRP as a regressor (or predictor) for leukocyte counts, but rather to improve the robustness of the model against infections by downweighting the outlying leukocyte counts when CRP is elevated." (PMID 31792398, 2019).
infection (continued). "Maternal infection during pregnancy was associated with a 7% lower CRP level (among offspring compared with offspring born to women without an infection (95% CI, − 17,5%) and similarly an 8% lower level of IL-6 (95% CI, − 15, 1%), and a 9% lower level of IL-10 (95% CI, − 23,20%)." (PMID 30923624, 2019). "Thus, the predictive value of CRP in acute stroke appeared to be altered by early infection." (PMID 30718369, 2019). "Furthermore, exclusion of patients with an early infection during hospitalization did not significantly affect the association of CRP with mortality." (PMID 30718369, 2019). "Therefore the observed levels of CRP and SAA during EVD in rhesus macaques may be higher than what would be expected from an infection caused by some common respiratory viruses." (PMID 30774579, 2019). "Moreover, while CRP is stimulated through pro-inflammatory cytokines that play a role in cell damage, fibrosis and scarring, these cytokines are also necessary to clear an infection." (PMID 31858023, 2019). "Indeed CRP levels in patients without a known cause for their infection are on average higher than those with an identified viral infection." (PMID 31245630, 2019). "A CRP-Genetic risk score (z-score) above 0 was also associated with higher hs-CRP: GM, 0.17 vs. 0.11 mg/L; GMR, 1.27, [95%CI: 1.15–1.40], p < 0.01, and likewise for having an infection 14 days prior to blood sampling: GM, 0.22 vs. 0.11 mg/L; GMR, 2.08 [95% CI: 1.70–2.54], p < 0.01." (PMID 30816254, 2019). "Among the identified potential metabolic biomarkers for CAP, the levels of sphinganine in the serum of CAP patients is lower than for controls, and it was observed positively correlated with NE%, ESR and CRP, so it might reflect the presence of an infection and inflammatory response." (PMID 29759075, 2018). "There may be other reasons for fever or elevation of CRP than infection in these patients." (PMID 29491477, 2018). "Furthermore, the pathogenic mechanism of serum CRP elevation is not understood in this type of infection." (PMID 30192893, 2018). "Firstly, since neither study excluded participants with very high CRP values, associations may have been inflated by infection- or injury-related fatigue, rather than the chronic processes ostensibly under investigation." (PMID 28994356, 2018). "Kingsley and Jones tested whether CRP could be used to distinguish different types of infections." (PMID 29706967, 2018). "CRP-cAMP is a regulator tailored to mediate rapid responses to environmental changes and may therefore be relevant for HilD-mediated regulation of virulence in response to the environmental conditions that Salmonella encounters through the infection process." (PMID 29879120, 2018). "However, the corresponding value in the moderate-infection group was only 30%; note that all surveys in this group only measured a single acute-phase protein (either CRP or AGP), and the ferritin adjustment had a relatively smaller impact on the prevalence of ID in these surveys." (PMID 28615260, 2017). "As such, it may be inferred, that CRP may not always be a sensitive enough marker to detect participants as risk of developing post-operative infections, following FURS." (PMID 28683066, 2017). "Also, the possibility that this anti-inflammatory influence would reduce CRP in the presence of multiple infections and vitamin deficiencies has not been previously considered." (PMID 28571565, 2017). "Indeed, Schmit and Vincent 18 reported the time course of CRP concentrations in 50 septic patients with adequate (n=24) or inadequate (n=18) empiric antibiotherapy and in surgical patients who needed reoperation for uncontrolled infection (n=8)." (PMID 28226029, 2017). "CRP has no sensitivity of 100%, so some cases of infection may go unrecognized because of low-grade infections or due to encapsulated bacteria associated with a less intense systemic response with a more modest rise of inflammatory markers." (PMID 29138696, 2017).
infection (continued). "Therefore, the differences in CRP could partially reflect the inclusion of women with severe and late stage infections, when the maternal inflammatory response is primarily activated." (PMID 26942752, 2016). "Therefore, our results question the place of CRP measurements for diagnosing infection on the ICU." (PMID 27597981, 2016). "Moreover, CRP values correlated well with the severity of the infection." (PMID 27782809, 2016). "At a threshold of 5 mg/L, CRP still has limited diagnostic value in ruling in serious infection (at most, 1 in 40 children will have serious infection) but it does rule out serious infection and the need for hospital referral." (PMID 27716201, 2016). "Similarly, baseline hepcidin values were low, indicating that the patient population did not have chronic inflammation (the study protocol excluded patients with active infection or baseline CRP ≥ 20 mg/L), limiting extrapolation to more inflamed patient groups." (PMID 27276035, 2016). "Additionally, marked or persistent elevation of CRP values should alert the clinician to possible continued infection; this study found that a CRP cutoff of 15 mg/dL had the best sensitivity/specificity profile for predicting when a single surgery alone was likely to fail." (PMID 27174186, 2016). "To assess whether ligand such as ES-62 present in serum during infection and CRP would alter complement activity, we added the nematode product to serum and then examined the ability of that serum to be activated by an IgM-driven classical complement pathway assay." (PMID 27044740, 2016). "However, we cannot exclude that subclinical infection could explain high values of C-reactive protein in the bonobos from Lola Ya Bonobo." (PMID 26247603, 2015). "In the context of the presented data and literature we suggest routine measurement of serum CRP levels in a continuous fashion from the day of admission, 2nd to 3rd, and 4th to 5th day postoperatively, as secondary relapse may help in detecting postoperative infection." (PMID 25585544, 2015). "The aim of this study was to investigate whether CRP and NLR could significantly improve the diagnostic accuracy of infection and advance the predictive power of short-term mortality in a large consecutive cohort of patients, who were hospitalized due to hepatic events." (PMID 26498833, 2015). "Early death by infection (within 100 days) resulted in 25 and 8.7% of patients with high CRP with and without documented infection, respectively (p < 0.001 and p = 0.04), compared to patients with normal CRP, where early death by infection occurred in 2.3% of patients." (PMID 26543528, 2015). "Furthermore, in a study examining incidence of infection in ICH patients, those that had infection had significantly larger hemorrhages, poorer National Institutes of Health Stroke Scale scores, raised levels of CRP and were more likely to experience intraventricular hemorrhage extension." (PMID 25705177, 2015). "We consider that a rise in CRP level after postoperative day 3 may indicate infection." (PMID 25888882, 2015). "In addition, CRP holds pragmatic advantages as it rises to higher concentrations in the presence of infection, which may allow more accurate and low cost point of care tests that rely on low volumes of whole blood." (PMID 26558692, 2015). "Therefore, CRP still has a reference value as an indicator of severe infection." (PMID 26259626, 2015). "Furthermore, CRP is produced and secreted by signaling hepatocytes in response to proinflammatory cytokines such as IL-1β and IL-6 and the lag time from the onset of infection until CRP elevation is 6 to 8 hours, possibly interfering with the usefulness of this measurement." (PMID 25667565, 2015). "Therefore, CRP has a clear role in monitoring response to treatment when infection is diagnosed." (PMID 25888882, 2015).
infection (continued). "A possible explanation for elevated CRP levels could be preceding interventions, as no relevant underlying disease such as infection and no heparin treatment as explanation for elevated aPTT levels were reported in the investigated study groups." (PMID 26620128, 2015). "Moreover, the CRP level in CAP was affected by a different infection source." (PMID 25371597, 2014). "Infection parameters (C-reactive protein and WBC count) may be normal or marginally raised." (PMID 25386377, 2014). "However, most patients had no symptoms or signs of clinical infection; thus, it is difficult to associate the higher CRP levels with a specific infection or inflammatory response." (PMID 25431593, 2014). "However, there is also a possibility that patients could consult more often based on the safety-netting advice in the patient booklet [ref trial] or if they believe it is important to be given a CRP test to exclude serious infection." (PMID 24238118, 2013). "However, persistent elevation of CRP raises the possibility of infection." (PMID 24288493, 2013). "CRP level was not an independent risk factor of postoperative infection." (PMID 23520452, 2013). "Likewise it seems unlikely that differences in CRP response could be explained by post-operative infection being more common as waist:hip ratio rises." (PMID 23391158, 2013). "Taken together, the CRP-286 (C>T>A) genotype polymorphism and specific IgG antibody subclass levels against neonates infected with S. aureus, may contribute to a reduced risk of EOS infection in neonates living in Saudi Arabia." (PMID 23941472, 2013). "However, in the current study, the negative association observed between CRP and retinol levels can also be the manifestation of vicious causal relationship between infection and VAD." (PMID 23930336, 2013). "However, well-designed studies have shown that PCT is neither a better nor an earlier diagnostic marker of infection than CRP." (PMID 23547830, 2013). "Thus PCT levels more accurately reflect the real-time extent of inflammation and may be more useful than CRP in the early diagnosis of infection and monitoring of disease." (PMID 23272177, 2012). "Hence our study aimed to assess the value of simultaneous measurement of PCT and IL-6 along with the white blood cell, neutrophil and lymphocyte count, blood culture and high sensitive C- reactive protein (hs-CRP) in neonate populations with a rapid diagnosis of the infection." (PMID 22708043, 2012). "However, recent evidence on the utility of the CRP test in patients with various infections suggests that there are great variations in the sensitivity, specificity, and predictive values of this test, which may compromise its diagnostic accuracy." (PMID 22943554, 2012). "Furthermore, because recent infections or illness might increase the CRP level, we performed an analysis restricted to participants who did not report a recent illness (n = 182), and an analysis excluding one participant whose CRP was > 10 mg/L." (PMID 21628108, 2011). "The importance of RCPF may have been expected, since the study was conducted in an area with a high infection pressure, reflected in a high prevalence of single or mixed infections, and in the fact that the majority of patients had a raised plasma CRP concentration." (PMID 20830291, 2010). "Hence, CRP cannot be used as a marker for infection in the early postoperative period." (PMID 20512289, 2009). "Baseline CRP in the absence of obvious causes like infection or inflammation may represent the chronic inflammatory status of a patient." (PMID 19400931, 2009). "Given the massive induction of CRP in response to acute inflammation or infection (up to and exceeding 500 mg/l) and the half-life of the protein in the circulation (19 h), it is feasible that CRP levels may remain over a significant level for a week after the initial elevation." (PMID 19732183, 2009).
infection (continued). "Co-IP confirmed that the CRP∶L-ficolin complex formation was induced in the serum by infection-inflammation condition (low pH, low calcium level and high CRP level) and ELISA demonstrated that L- and M- ficolins displayed stronger binding to CRP when the latter was anchored first to bacteria." (PMID 19180241, 2009). "Since CRP can be elevated by as much as 1000-fold over baseline (~100 μg/L to as much as 500 mg/L), monitoring is considered very useful, not just for screening, but also for disease management since the level reflects not only the presence, but also intensity of inflammation or infection." (PMID 18445267, 2008). "Including the general clinical condition, antibiotic pre-treatment and a substantial rise of CRP into the decision, whether or not to obtain blood cultures from medical inpatients with a suspected infection, could improve the diagnostic yield." (PMID 18957115, 2008). "Although NNIS scores, in association with other acute-phase proteins such as CRP, albumin and prealbumin, and with IL-6, were not the most effective tool, they may enable more accurate prognoses for postoperative infection." (PMID 17505683, 2007). "NNIS, albumin, CRP and IL-6 may be useful as predictive markers for postoperative infections." (PMID 17505683, 2007). "Therefore CRP seems to be a sensitive but less specific marker of infection." (PMID 17598889, 2007). "In addition one control subject, who had CRP values > 10 mg· L-1, was excluded from the analysis as CRP values of this order may be indicative of infection or trauma." (PMID 16716211, 2006). "• Four CRP patterns could be identified in infected patients before infection diagnosis and in noninfected patients before ICU discharge, which showed diverse associations with prediction of infection." (PMID 16635270, 2006). "Also, high levels of human CRP protect against lethal infection." (PMID 15456513, 2004). "Monitoring serological parameters (e.g., CRP and Anti-CCP), skin/mucosal symptoms, and signs of infection is recommended during combination therapy to support medication safety." (PMID 41836963, 2026). "P-SEP rises very early after the onset of infection; detectable increases can occur within 2–3 h after bacterial stimulation, often preceding PCT and CRP." (PMID 41597433, 2026). "By Month 6, short-term infection control was achieved in 96.7% of patients, with significant reductions in ESR and CRP (both p < 0.001)." (PMID 42072991, 2026). "CRP and SAA are rapidly upregulated in response to infection and contribute to pathogen recognition, opsonization, and inflammation." (PMID 41596719, 2026). "Of the 9 TN-specific proteins, 6 proteins (CRP, LBP, LRG1, SAA1, TFRC) overlapped with the WT group identifying them as infection-specific and toxin-independent proteins (black text)." (PMID 41326716, 2026). "Against clinical infection, DNI outperformed others (AUC:0.921; ΔAUC vs. CRP = 0.204, ESR = 0.343, WBC = 0.244, PCT = 0.295; all p < 0.001)." (PMID 41598776, 2026). "Few infants had normal infection indicators within 24 h, and although WBC levels normalized by 24-48 h, CRP levels remained elevated." (PMID 41624828, 2026). "We systematically surveyed and summarized evidence from experimental and clinical studies describing "function of CRP and SAA during infection", "CRP and SAA in innate immune defense", and "evasion mechanisms across bacterial, viral, and fungal pathogens"." (PMID 41596719, 2026). "In all patients, MDW yielded the highest AUC for discrimination of infection (AUC 0.856), followed by PCT (AUC 0.824) and CRP (AUC 0.798)." (PMID 41303127, 2025). "With satisfactory infection control achieved (maximum temperature 36.9 °C, WBC 3.46 × 109/L, CRP 49.98 mg/L), intravenous imipenem-cilastatin was replaced by oral amoxicillin-clavulanate potassium tablets on April 9 (1.0 g orally, every 12 h)." (PMID 41234929, 2025).